IL10 (interleukin 10)
Diseases named in the same sentence as IL10 in open-access papers (continued):
Sharing a sentence is not in itself a finding about the gene and the disease.
tuberculosis (continued). "The corresponding serum samples showed significantly higher concentrations of IL-10 and IL-22 protein in tuberculosis-IRIS patients." (PMID 23303806, 2013). "Experimental evidence also suggests that use of IL-10 specific neutralizing antibody resulted in enhancement of tuberculosis proliferation." (PMID 24147054, 2013). "At 24 hours, several of the cytokines (IL-10, IL-20, and IL-26) had significantly higher transcript levels in the stimulated tuberculosis-IRIS cultures (P < .001, P = .022, and P = .004, respectively)." (PMID 23303806, 2013). "In this study, we show that consistently higher levels of IL-10 mRNA and serum protein were observed in tuberculosis-IRIS patients." (PMID 23303806, 2013). "It is interesting that levels of IL-22 gene expression and serum protein were, like those of IL-10, found to be significantly higher in tuberculosis-IRIS patients." (PMID 23303806, 2013). "In summary, our findings show elevated levels of IL-10 and IL-22 in patients with tuberculosis-IRIS." (PMID 23303806, 2013). "In experimental tuberculosis, NOD knockout mice were similarly susceptible to M. tuberculosis infection while NOD-deficient DCs produced less IL-12 as well as IL-6 and IL-10 upon stimulation with mycolylarabinogalactan peptidoglycan." (PMID 23805193, 2013). "Production of IL-10 has also been reported to be higher in patients who had active tuberculosis, compared with tuberculin skin test responders." (PMID 23303806, 2013). "Significantly higher concentrations of IL-10 (P = .0004) were detected in the serum of tuberculosis-IRIS patients (median, 875.6 pg/mL [interquartile range {IQR}, 64.5–9982 pg/mL]), compared with non-IRIS patients (median, 137.2 pg/mL [IQR, 24.3–1346 pg/mL])." (PMID 23303806, 2013). "There was an inverse correlation between the serum concentrations of IL-10 and IL-22 (Spearman r = −0.69; P = .007) in the tuberculosis-IRIS group." (PMID 23303806, 2013). "IFNγ and IL-10 producing CD4+ T cell clones were first obtained in active tuberculosis patients and patients with Lyme disease." (PMID 23152883, 2012). "In human tuberculosis, IL-10 production is higher in anergic patients, suggesting that M. tuberculosis induces IL-10 production, suppressing an effective immune response." (PMID 23251798, 2012). "Previously we observed enrichment of Treg cells among tuberculosis patients and their role in suppression of effector T cell response via Interluekin-10 (IL-10)." (PMID 23028594, 2012). "The best fit model found was log(P(Tuberculosis)/P(sarcoidosis)) = 1.214 + 8.884 * IL1 + 0.075 * IFN + 0.32 * IL12p70 + 0.039 * TNF − 0.097 * IL5 − 0.015 * IL8 − 0.73 * IL13 − 0.606 * IL10 − 2.404 * IL2 − 4.231 * IL4." (PMID 22815689, 2012). "Macrophages from patients suffering from tuberculosis are suppressed in vitro, and the inhibition of IL-10 reverts partially this suppression." (PMID 23251798, 2012). "Previously, we demonstrated IL-10 mediated suppression of T cell response among tuberculosis patients, Here, we showed PD-1 mediated contact dependent suppression of Mtb. specific T cell response." (PMID 23028594, 2012). "Firstly, Treg cells play important role in suppression of protective T cell response among tuberculosis patients via IL-10 and PD-1 pathway." (PMID 23028594, 2012). "Due to its regulatory profile, it is likely that IL-10 induction during tuberculosis will affect the course of disease." (PMID 23239994, 2012). "The objective of the current study was to analyze the frequency of cytokine gene polymorphisms linked to high and low responder phenotypes (IFNγ +874 Thi→Alo and IL10 −1082 Glo→Ahi) in tuberculosis patients." (PMID 19274101, 2009). "We have recently reported that the ratio of two key cytokines (IFNγ and IL10) show significant correlation with the severity spectrum of tuberculosis." (PMID 19274101, 2009).
tuberculosis (continued). "We have now extended these studies to analyze the frequency of high and low responder cytokine phenotypes (IFNγ +874 Thi→Alo and IL10 −1082 Glo→Ahi) to analyze the relationship of these SNPs with clinical severity of tuberculosis." (PMID 19274101, 2009). "Responses of whole blood PBMC to PPD and other mycobacterial antigens are reduced in active tuberculosis probably due to suppressor T cells (Tregs ) or cytokines, e.g. IL-10 or TGF-β." (PMID 19753300, 2009). "IFNγ in coordination with IL10 plays a key role in protective immunity against M. tuberculosis by regulating effector responses in tuberculosis." (PMID 20041183, 2009). "Furthermore, in peripheral blood mononuclear cells (PBMC) from tuberculosis patients, blocking of IL-10 resulted in higher lytic activity of CD4+ and CD8+ cells." (PMID 40939292, 2025). "IL-6, IP-10, IL-10, and IL-22 were detectable in the majority of tuberculosis patients (> 50%), whereas IFNγ and GM-CSF were measurable only in minor subsets of both study groups (IFNγ: 41.1% in patients, 25.0% in contacts; GM-CSF: 21.4% in patients, 2.5% in contacts)." (PMID 35759173, 2023). "Similarly, the concentration of IL-6 was significantly increased and IL-4 decreased in SA, and the concentrations of INF-γ, IL-2, IL-4 and IL-10 were significantly lower in tuberculosis, compared to those in healthy subjects." (PMID 36982159, 2023). "Notably, IL-6/IL-10 ratios showed strongest capacity to discriminate TB-Sp and TB-Pb (AUC: 0.88, p < 0.0001), suggesting that opposing IL-6 and IL-10 levels characterize these tuberculosis patient subgroups." (PMID 35759173, 2023). "We as well as others found higher expression of IL-10 in tuberculosis patients." (PMID 35759173, 2023). "Therefore, we predicted central DEGs in the PPI network and noted strong interactions between TNF, IL-6, IL-10, IL-1β, CSF-2, IL-4, CXCL8, IFN-γ, IL-1α, and CXCL1, all of which are strongly associated with tuberculosis." (PMID 37818041, 2023). "In conclusion, we observed that a combination of IL-6, IL-10 and IP-10 could potentially differentiate between tuberculosis patients with different mycobacterial burden." (PMID 35759173, 2023). "The IL-10 gene polymorphisms (rs1800896) that limit or decrease the expression of IL10, are implicated in susceptibility to pulmonary infection and inflammation, such as tuberculosis (PTBC) and ARDS, specifically in the adult and elderly." (PMID 36428884, 2022). "An observed elevation of antibodies occurring in advanced tuberculosis may be coordinate with increased IL-10, much as we see with clinical paratuberculosis." (PMID 36477266, 2022). "IL-10 is an important inflammatory immunosuppressive cytokine during tuberculosis immunity that can inhibit the formation of phagosomes in macrophages and weaken the antigen-presenting effect of macrophages, thereby reducing the clearance effect of the immune system against M. tuberculosis." (PMID 36081511, 2022). "Among the various cytokines, pro-inflammatory cytokines (TNF-α, IL-6, and IL-1β), and Th1 cytokines (IL-12, IFN-γ, and IL-2) are known to confer significant protection against tuberculosis, while anti-inflammatory cytokines (IL-10 and TGF-β) and type-I interferons (IFN-β) confer susceptibility." (PMID 35832818, 2022). "Moreover, miR-23a-3p was shown to inhibit monocyte function and phagocytosis by targeting IRF1/SP1 followed by the TLR4/TNF-α/TGF-β1/IL-10 signaling pathway in patients with active tuberculosis." (PMID 34608568, 2021). "In line with this, it has been shown that the ratio of IFNγ and IL10 correlates with disease severity of tuberculosis and may differentiate pulmonary from extra-pulmonary forms." (PMID 33767693, 2021). "IL10 and IL-5 levels were lower in latently infected individuals than tuberculosis patients." (PMID 32962082, 2020).
tuberculosis (continued). "Transcript and protein levels of the anti-inflammatory cytokine IL10 were also examined, the expression of which has been shown to promote tuberculosis disease progression and Mtb pathogen persistence in CBA/J mice, and blocks phagosome maturation in hMDMs and hAMs." (PMID 32477344, 2020). "Upregulation of IL-10 during tuberculosis treatment might be considered as a protective factor against lung dysfunction." (PMID 31363402, 2019). "The ability of IL-10 to downregulate immune responses and the fact that IL-10 can be detected in tuberculosis patients have led us to investigate whether IL-10 plays a role in BCG vaccination efficacy." (PMID 31281230, 2019). "Indeed, blocking GM-CSF triggered the overproduction of anti-inflammatory IL-10, while TNFα and IL-12, pro-inflammatory cytokines which play a key role for the host-response to tuberculosis, were reduced." (PMID 29872095, 2018). "Accordingly, mouse models of tuberculosis have indicated that IL10 deficient mice show no mortality until ca. 14 wpi16 indicating a significant adaptive immune component in infection control." (PMID 29985419, 2018). "IL10 has been widely studied for its potent role in tuberculosis." (PMID 29985419, 2018). "Due to its negative effect on protective adaptive immune responses, IL-10 signaling has been associated with detrimental course of infection in experimental tuberculosis in mice." (PMID 29312298, 2017). "The ability of IL-10 to down-regulate immune responses and the fact that IL-10 can be detected in tuberculosis patients have led researchers to investigate whether IL-10 plays a role in susceptibility to tuberculosis." (PMID 24523896, 2014). "Another study found that historical statistics supported a hypothesis linking TB and air pollution caused by coal, which was proposed whereby triggering of the interleukin-10 cascade by carbon monoxide in lung macrophages promotes the reactivation of Mycobacterium tuberculosis." (PMID 24929074, 2014). "We also observed the involvement of other receptor in the production of IL-10 during tuberculosis." (PMID 24695099, 2014). "This suggests that, although the early production of IL-10 in response to tuberculosis may be detrimental, this cytokine is ultimately necessary to prevent immunopathology." (PMID 23303806, 2013). "The concomitant increase in Th1 cytokines and IL-10 may reflect the induction of distinct populations, which act together in the establishment of clinical cure of tuberculosis, or of IFN-γ/IL-10 double-producing populations." (PMID 23824716, 2013). "The Vδ2+ T cell percentages in the BALF of all tuberculosis patients were lower than in their peripheral blood (P <0.05), and IL-4 and IL-10 concentrations in peripheral blood of anergic tuberculosis patients were higher than in TST-positive tuberculosis patients and healthy controls (P <0.05)." (PMID 23936496, 2013). "In addition, we suggest that high expression of FasL triggers Vδ2+ T cell apoptosis, and increased IL-4 and IL-10 secretion induce an impairment of Vδ2+ T cell-mediated anti-tuberculosis immunity." (PMID 23936496, 2013). "We hypothesize that the high levels of IL-10 observed in the peripheral blood of tuberculosis-IRIS patients in this study reflect an overspill of IL-10 from the sites of inflammation where IL-10 would be involved in regulating and resolving inflammation." (PMID 23303806, 2013). "The higher levels of IL-10 observed in this study may represent a compensatory antiinflammatory response during tuberculosis-IRIS." (PMID 23303806, 2013). "IL-10 may be required to modulate proinflammatory effects in patients and in healthy household tuberculosis individuals." (PMID 23251798, 2012). "However, there are few reports in the literature on the production of IL-10 by household contacts of patients with tuberculosis." (PMID 23251798, 2012). "IL-10 is also able to induce the reactivation of tuberculosis in animals." (PMID 23251798, 2012).
tuberculosis (continued). "This may be particularly relevant at mucosal surfaces, since human studies have implicated functional SNPs in the IL10 gene as risk factors for IBD and tuberculosis." (PMID 20398313, 2010). "Tuberculosis-driven IL-10-producing T cells might down-regulate human IL-22 and IL-17 producing Th17 cells in chronically-active TB." (PMID 20195465, 2010). "However, and with regard to the sample size and the robustness of case and control phenotypes, in particular the exposure of PPD-negative controls to M. tuberculosis, our results make a contribution of IL10 promoter haplotypes to the polygenic mosaic of TB susceptibility likely." (PMID 19412539, 2009). "Neither IL10 −1082 genotype nor alleles show any association in relation to either site or severity of tuberculosis." (PMID 19274101, 2009). "Higher production of IFNγ relative to IL-10 in P3 may reflect Mtb-specific immunological memory as a consequence of previous tuberculosis." (PMID 18442415, 2008). "The IFN-γ (+874) AA and IL-10 (−1,082) AG genotypes were more prevalent among TB patients infected with the SIT745/EAI1-MYS M. tuberculosis strains compared to non-SIT745/EAI1-MYS, indicating a possible link between these genotypes and more severe TB symptoms." (PMID 40487054, 2025). "Additionally, the TYK2:p.Pro1104Ala variant selectively impairs cellular responses to IL23, but not to IFN‐alpha or IL10, in agreement with its predisposing effect for tuberculosis." (PMID 39835539, 2025). "Additionally, patients with HTLV-1-associated myelopathy and tuberculosis exhibit higher TNF/IL-10 and IFN-γ/IL-10 ratios compared to those without TB." (PMID 39772183, 2024). "Some cytokines resulting from the activation of T lymphocytes and phagocytic cells, such as IFN-γ and TNF-α, are efficient in controlling infection, while others may contribute to the survival and growth of Mtb or mediate susceptibility to tuberculosis, including IL-4, TGF-β, and IL-10." (PMID 37892223, 2023). "In addition, reduced apoptosis in tuberculosis may be due to a higher production of IL-10 than TNF-α and NO, which is controlled by low expression of the SLC11A1 (formerly NRAMP) gene encoding macrophage protein 1, which is associated with natural resistance." (PMID 36982159, 2023). "We, therefore, characterised and compared the expression of IL-6, TNF-α, IFN-γ, and IL-10 in whole blood of treatment naïve TB patients stimulated with heat-killed Mycobacterium tuberculosis stratified by HIV status and the level of CD4 count." (PMID 35025927, 2022). "After infection with M. Tuberculosis, mice with IL-10 hypersecretion showed an accelerated progression of TB infection and signs of TB reactivation." (PMID 34835417, 2021). "We considered the characteristic anti-inflammatory and tissue protective properties of IL-10 in lung and CNS on the one hand and its ability to inhibit antimicrobial immunity in the lung and to further chronification including of coronavirus CNS infection and tuberculosis on the other." (PMID 33746948, 2021). "Similarly, a negative modulation of IL-10 was observed, which despite being described as a regulatory cytokine has been associated with the clinical cure of patients with tuberculosis and experimental models have associated its production with IFN-γ/IL-10—double producers T cells." (PMID 29543912, 2018). "In accordance with the acquisition of this anti-inflammatory profile, TB-PE-induced FM secreted higher levels of IL-10 and lower levels of TNF-α upon stimulation with irradiated Mycobacterium tuberculosis (iMtb) than untreated cells." (PMID 29593722, 2018). "Thus, it would be interesting to investigate whether anti-tuberculosis vaccines including those formulated with TDB or other Mincle ligands can be combined with anti-IL-10 antibodies to improve both, efficacy and duration of protection against M. tuberculosis." (PMID 29312298, 2017).
tuberculosis (continued). "More recently, a regulatory role for B cells has been described in TB granulomas in primates, which is mediated via secretion of IL-10 and M. tuberculosis-specific antibodies." (PMID 26423994, 2016). "Low to no IFN-γ, IL-12, IL-2 and IL-10 successfully discriminated non-infected mice from infected mice but failed to discriminate disease status amongst supersusceptible, susceptible and resistant M.-tuberculosis-infected DO mice." (PMID 26204894, 2015). "CD4+ T cell expression of IL-10 is an important mechanism controlling immunity to tuberculosis (TB)." (PMID 26417443, 2015). "This study describes a scenario in which potentiation of CD4+ and CD8+ T cell activation and increased Th1 cytokine production are associated with the clinical cure of tuberculosis in the absence of significant changes in Th2 cytokine production and is accompanied by increased production of IL-10." (PMID 23824716, 2013). "The coexpression of IL-10 and IL-22 seen in our study and their inverse correlation in tuberculosis-IRIS patients supports the suggestion that there may be interaction between these cytokines in this condition (and not in controls), as has been postulated for other diseases." (PMID 23303806, 2013). "IL-10 has also been thought to be responsible for the suppression of immune response against TB, and persistence of a long-term M. tuberculosis infection." (PMID 24455461, 2013). "Th1 immune responses (IFN-γ, IL-12) are required for protection against infection with M. tuberculosis while a raised Th2-like cytokine profile (such as, IL-10, IL-4 and TGF-β) is implicated with disease progression in TB." (PMID 23320781, 2013). "Our previous studies have also shown that monocytes and generated in vitro DCs from pulmonary tuberculosis (TB) patients are remarkable for increased interleukin-10 production." (PMID 23056139, 2012). "M. tuberculosis-induced IL10 levels were significantly raised in TB patients as compared with both TST- and TST+ ECs (p<0.001, Kruskal Wallis test)." (PMID 20041183, 2009). "Leucocyte activating chemokines such as CCL2, CCL3, and CXCL8 together with proinflammatory IFNγ, TNFα and downmodulatory IL10 play a central role in the restriction of M. tuberculosis infections, but is unclear whether these markers are indicative of tuberculosis disease severity." (PMID 20041183, 2009). "Increased M. tuberculosis- and M. bovis BCG - induced CCL2 and IL10 and decreased IFNγ responses in TB patients." (PMID 20041183, 2009). "IFN-γ is a key pro-inflammatory cytokine produced by natural killer (NK) cells and T-helper-1 (Th1) cells that mediates immunity to TB, especially by activating macrophages and other immune cells, including IL-10 and tumor necrosis factor-alpha (TNF-α), to kill M. tuberculosis." (PMID 40487054, 2025). "Six cytokines, i.e., IL-6, IP-10, IL-10, IL-22, IFN-γ, and GM-CSF, were significantly higher in plasma samples from patients with tuberculosis." (PMID 35759173, 2023). "IL6, IL10, pSTAT3, and SOCS3 have been identified as influential factors distinguishing tuberculosis patients from healthy individuals." (PMID 37834286, 2023). "Similar to tuberculosis with HIV superinfection in mice, we observed increased levels of IL-10 and IL-6 in superinfected tissues compared to those in both the SARS-CoV-2-alone and tuberculosis-alone groups." (PMID 36200898, 2022). "The tuberculosis patients showed a positive correlation between IFN-γ levels and FASL expression levels, but these patients had higher IL-10 levels than IFN-γ levels." (PMID 36671466, 2022). "The enhanced levels of IL-10 and TGF-β in the lungs of active tuberculosis patients demonstrate a weakened immune response to M. tuberculosis, and hence, a role in the pathogenesis and disease progression." (PMID 29867915, 2018).